FUBP1 (far upstream element binding protein 1)
Diseases named in the same sentence as FUBP1 in open-access papers (continued):
Sharing a sentence is not in itself a finding about the gene and the disease.
clear cell renal cell carcinoma (4 papers, 2017 to 2022). "It is noted that FUBP1 also can promote the proliferation and deterioration of renal clear cell carcinoma." (PMID 35546072, 2022). "However, the expression pattern and potential biological function of FUBP1 in clear cell renal cell carcinoma (ccRCC) is yet to be established." (PMID 28076379, 2017).
colorectal cancer (4 papers, 2017 to 2023). A primary or metastatic malignant neoplasm that affects the colon or rectum. "In this research, we aimed to identify the effects of FUBP1 on promoting colorectal cancer stemness and metastasis and the underlying mechanism." (PMID 34288405, 2021). "According to previous results, the “P3” segment (-1422 ~ -1261) of the 2 kb downstream of DVL1 was the binding site of FUBP1 in colorectal cancer." (PMID 36932454, 2023). "The conclusion of the mechanism study fully revealed the reason for the increase in FUBP1 in colorectal cancer, providing another target for treatment." (PMID 34288405, 2021). "A previous study indicated that FUBP1 could promote DVL1 transcription to activate Wnt/β‐catenin pathway in colorectal cancer." (PMID 36932454, 2023). "Meanwhile, FUBP1 was shown to promote DVL1 transcription in colorectal cancer." (PMID 36932454, 2023). "Moreover, PVT1 expression was up-regulated in colorectal cancer tissues, which correlated with the expression of MYC and many MYC regulating genes FUBP1, EZH2, and NPM1." (PMID 29108264, 2017).
leukemia (4 papers, 2020 to 2023). A malignant (clonal) hematologic disorder, involving hematopoietic stem cells and characterized by the presence of primitive or atypical myeloid or lymphoid cells in the bone marrow and the blood. "FUBP1 was found to be overexpressed in murine leukaemia models, with its knockdown resulting in increased survival and apoptosis." (PMID 36478132, 2023). "It has been reported that knockdown of FUBP1 in murine models of chronic and acute myeloid leukemia as well as leukemia cells resulted in prolonged survival and decreased cell cycle activity." (PMID 35274005, 2022). "In addition, the expression level of FUBP1 was explored using the CCLE database, and it was demonstrated that FUBP1 was highly expressed in embryonal cancer, neuroblastoma and leukemia compared with other solid tumors." (PMID 35274005, 2022).
neuroblastoma (4 papers, 2019 to 2022). Neuroblastoma (NB) is the most common solid, extracranial childhood tumor. "In neuroblastoma, FUBP1 was found to promote the development of tumor cells by targeting HIF-1α and enhancing glycolysis." (PMID 35274005, 2022). "FUBP1 mRNA levels were increased along with the increase in International Neuroblastoma Staging System (INSS) stages." (PMID 31511046, 2019). "However, the expression of FUBP1 in neurogenic tumours is still unclear, and its expression level and effect in neuroblastoma should be further studied." (PMID 31511046, 2019). "In addition, FUBP1 protein levels were remarkably increased with NB malignancy in the NB tissue microarray (NB: n = 65; ganglioneuroblastoma: n = 31; ganglioneuroma: n = 27)." (PMID 31511046, 2019). "Furthermore, the NB transcriptome data from the GEO database were analysed, and we found that FUBP1 mRNA was augmented with the rise in the International Neuroblastoma Staging System (INSS) stage." (PMID 31511046, 2019). "The results implied that LDHA could be regulated by FUBP1, but previous study demonstrated that LDHA promoted neuroblastoma growth independent of aerobic glycolysis." (PMID 31511046, 2019).
ovarian carcinoma (4 papers, 2021 to 2025). A malignant neoplasm originating from the surface ovarian epithelium. "According to the TCGA and GTEx datasets, the expression of FUBP1 in ovarian cancer tissue was lower than that in normal tissues." (PMID 35274005, 2022). "However, previous studies reported that knockdown of FUBP1 in SKOV-3 ovarian cancer cells reduced tumor burden in a nude mouse model." (PMID 40565351, 2025). "Similarly, analyses using online databases by others also showed increased FUBP1 expression in ovarian cancer compared to normal ovarian tissues." (PMID 40565351, 2025). "Further studies are warranted to investigate the role of FUBP1 in ovarian cancer." (PMID 40565351, 2025). "In addition, previous studies have shown increased FUBP1 expression in ovarian cancer tissues compared to normal tissues using IHC." (PMID 40565351, 2025). "We validated the expression of proteins of interest (COL12A1, FUBP1, PLEC, SLC4A1, and TKT) using immunohistochemistry (IHC) and further characterized their expression in online ovarian cancer databases." (PMID 40565351, 2025). "Previously, we confirmed ICA-mediated inhibition of FUBP1 expression in SKOV3, a human ovarian cancer cell line Thus far, FUBP1 expression and function in chondrocytes have not been fully studied, and the relationship between FUBP1 and HIF-1α/2α in chondrocytes is unclear." (PMID 37637163, 2023).
viral infection (4 papers, 2017 to 2026). "In contrast, FUBP1 was reported negatively regulating viral infection, as FUBP1 moved from the nucleus to the cytoplasm during the early stages of JEV infection and bound specifically to the JEV 5′UTR and 3′UTR to inhibit viral replication." (PMID 34794468, 2021). "Although three nuclear localization signals (NLS) confers the enrichment of Fubp1 in the nucleus, Fubp1 could translocate to the cytoplasm under various stimuli including viral infection and apoptosis to control mRNA stability or translation of its target genes." (PMID 32481602, 2020).
acute myeloid leukemia (3 papers, 2021 to 2025). Acute myeloid leukemia (AML) is a group of neoplasms arising from precursor cells committed to the myeloid cell-line differentiation. "Such mutations, including hotspots in SF3B1 and U2AF1 and loss-of-function events in FUBP1, RBM5, RBM10, and ZRSR2, are recurrent in myelodysplastic syndromes, acute myeloid leukemia, chronic myelomonocytic leukemia, and multiple solid tumors 8,42–45." (PMID 41279721, 2025).
astrocytic tumor (3 papers, 2012 to 2017). A glial tumor of the brain or spinal cord showing astrocytic differentiation. "In contrast, CIC and FUBP1 mutations were rare in primary GBMs (1% and 2%, n=94) and completely absent (0%, n=59) in grade II-III pure astrocytic tumors." (PMID 22869205, 2012).
brain cancer (3 papers, 2012 to 2025). A primary or metastatic malignant neoplasm affecting the brain. "Among the other transcription factors that we found among colon transcriptomics features Irx2, Pou4f1, Pou6f1, Tfap2a, Ctdp1, and Msx1 are known to be involved in neuronal development or closely related processes 31–37, and Fubp1 in brain cancer." (PMID 40791429, 2025). "Moreover, the protein expression of FUBP1 in pediatric brain cancer was found to differ across different races, showing high expression in Asian children compared with African-American and Caucasian children (p < 0.001)." (PMID 35274005, 2022).
endometrial cancer (3 papers, 2020 to 2021). Primary or metastatic malignant neoplasm involving the endometrium (mucous membrane that lines the endometrial cavity). "In an opposite fashion, NORAD works as a tumor suppressor by binding FUBP1 and promoting cell apoptosis in endometrial cancer." (PMID 33739352, 2021).
oligodendroglial tumor (3 papers, 2013 to 2017). Oligodendrogliomas are cerebral tumors that are differentiated from other gliomas on the basis of their unique genetic characteristics and better response to chemotherapy. "We were able to show here that CIC mutations are common in oligodendroglial tumors with 1p/19q co-deletion whereas FUBP1 mutations seem to occur more rarely." (PMID 24086756, 2013). "Therefore, the detection of mutations in CIC and FUBP1 marks an important step in deciphering the process of oligodendroglial tumor development." (PMID 24086756, 2013).
prostate carcinoma (3 papers, 2019 to 2025). A carcinoma that arises from epithelial cells of the prostate gland. "Higher FUBP1 expression is associated with earlier biochemical recurrence in prostate cancer patients." (PMID 39146021, 2024). "Suppressed prostate cancer progression was observed in various genetic mouse models expressing the FUBP1 mutant deficient in PRMT5-mediated methylation." (PMID 39146021, 2024). "Deficiency in FUBP1 methylation delays prostate cancer progression in vivo." (PMID 39146021, 2024). "The function of FUBP1 methylation in prostate cancer was also investigated in a mouse model with prostate-specific Probasin-mediated Pten deletion." (PMID 39146021, 2024). "FUBP1 knockdown strikingly impeded the development of prostate cancer in vivo, as indicated by xenograft weight and volume." (PMID 39146021, 2024). "A competitive peptide blocking FUBP1 methylation effectively suppresses prostate cancer development." (PMID 39146021, 2024). "Overall, our findings suggest that targeting FUBP1 methylation provides a potential therapeutic strategy for prostate cancer management." (PMID 39146021, 2024). "A subtle function of FUBP1 seems to be involved in different pathological environments, and its role in prostate cancer remains largely unexplored." (PMID 39146021, 2024). "Endogenous PRMT5, FUBP1, and meFUBP1 were detected in all prostate cancer–related cell lines, highlighting that the PRMT5-mediated FUBP1 methylation is a universal event in prostate cancer." (PMID 39146021, 2024). "To investigate the effect of FUBP1 methylation on prostate cancer, we established FUBP1-depleted LNCaP and C4-2 cell lines and reintroduced wild-type FUBP1 or FUBP13K at physiologically relevant levels." (PMID 39146021, 2024). "Together, these results demonstrate that FUBP1 and its methylation facilitate disease progression in patients with prostate cancer." (PMID 39146021, 2024). "Here we found that PRMT5 methylates FUBP1 at R359/R361/R363, which was important for the oncogenic effect of FUBP1 in prostate cancer." (PMID 39146021, 2024). "The expression of PRMT5, FUBP1, and meFUBP1 seems to be correlated in prostate cancer cell lines, supporting a potential biomarker role of meFUBP1 for PRMT5 activity." (PMID 39146021, 2024). "The mice were euthanized at the age of 15, 25, or 30 weeks for histopathological analysis to investigate the effect of Fubp1 methylation in prostate cancer at different stages." (PMID 39146021, 2024). "Here, we show that FUBP1 and its methylation were essential for prostate cancer progression, and a competitive peptide interfering with FUBP1 methylation suppressed the development of prostate cancer." (PMID 39146021, 2024). "Together, these data demonstrate that FUBP1 methylation promotes the development of prostate cancer." (PMID 39146021, 2024). "FUBP1 methylation is essential for its oncogenic effect, and the correlation of FUBP1 methylation with prostate cancer progression was validated in different mouse models and clinical specimens." (PMID 39146021, 2024). "Here, by investigating the function and modification of FUBP1 in prostate cancer, we found that the BRD4-PRMT5-FUBP1 axis is essential for prostate cancer progression." (PMID 39146021, 2024). "We also determined that nanocomplex (NC) delivery of a competitive peptide to block interaction of FUBP1 with PRMT5 is a potential therapeutic strategy to treat prostate cancer by preventing PRMT5-mediated FUBP1 methylation." (PMID 39146021, 2024). "In summary, we report that the BRD4-PRMT5/MTAP axis regulates FUBP1 methylation and is essential for prostate cancer progression." (PMID 39146021, 2024). "Alterations in RNA splicing were also observed in FUBP1-knockout cell lines, indicating that multiple mechanisms are involved in the oncogenic function of FUBP1 in prostate cancer." (PMID 39146021, 2024). "The effect of FUBP1 methylation on prostate cancer progression." (PMID 39146021, 2024).
prostate carcinoma (continued). "FUBP1 accelerated prostate cancer development in various preclinical models." (PMID 39146021, 2024). "Together, these data demonstrate the oncogenic effect of FUBP1 in prostate cancer." (PMID 39146021, 2024). "Oncogenic effects and modifications of FUBP1 in prostate cancer." (PMID 39146021, 2024). "The genomic aberration of prostate cancer cells, with a varied chromatin 3D structure, may lead to dysregulation of c-Myc and P21 by FUBP1." (PMID 39146021, 2024). "Together, these results support the oncogenic effect of FUBP1 methylation in prostate cancer." (PMID 39146021, 2024). "Here, we investigated the function and modification of FUBP1 in prostate cancer." (PMID 39146021, 2024). "As PRMT5-mediated FUBP1 methylation is not limited to prostate cancer, the clinical application of this competitive peptide may extend to other cancers, and HA/BPAE/peptide NCs could be used to treat various cancers with reduced systemic side effects and improved therapeutic efficacy." (PMID 39146021, 2024). "Thus, FUBP1 methylation could be a biomarker for prostate cancer progression." (PMID 39146021, 2024). "A competitive peptide, which was delivered through nanocomplexes, disrupted the interaction of FUBP1 with PRMT5, blocked FUBP1 methylation, and inhibited prostate cancer development in various preclinical models." (PMID 39146021, 2024). "A competitive peptide (PUBLISH), originated from the minimal interaction domain in FUBP1 mediating PRMT5-FUBP1 interaction, effectively blocked PRMT5-mediated FUBP1 methylation and successfully suppressed the development of prostate cancer." (PMID 39146021, 2024). "Considering the importance of FUBP1 methylation in prostate cancer, upstream signaling regulating PRMT5-mediated FUBP1 methylation was assessed." (PMID 39146021, 2024). "Previously reported oncogenic genes for prostate cancer, including SLC7A11 and pyruvate dehydrogenase kinase 1 (PDK1), were also suppressed after FUBP1 knockdown at both mRNA and protein levels in prostate cancer cells." (PMID 39146021, 2024). "The oncogenic effect of PRMT5-mediated FUBP1 methylation is unlikely to be limited to prostate cancer." (PMID 39146021, 2024). "Concurrently, cell proliferation was dramatically inhibited after FUBP1 knockdown in various prostate cancer cell lines but not in RWPE1, a normal prostate epithelial cell line." (PMID 39146021, 2024). "Higher expression of FUBP1 was found in prostate cancer compared with the adjacent normal tissue." (PMID 39146021, 2024). "Posttranslational modification may affect the function of FUBP1 in different pathological environments, but it has not been thoroughly investigated, especially in prostate cancer." (PMID 39146021, 2024).
anaplastic oligodendroglioma (2 papers, 2013 to 2023). A WHO grade III oligodendroglioma with focal or diffuse malignant morphologic features (prominent nuclear pleomorphism, mitoses, and increased cellularity). "Based on aCGH data and limited analysis of exome sequencing, the tumor reported here has a common anaplastic oligodendroglioma genomic profile including FUBP1, CIC, and IDH1 mutations." (PMID 23527265, 2013). "The pathological diagnosis was anaplastic oligodendroglioma (WHO grade III), with IDH1:p.R132H, PIK3R1:p.G376R, CIC:p.N205S, and FUBP1:p.Y505Gfs*16 mutations confirmed as driver genes in tumor tissue." (PMID 37533228, 2023). "Only twelve of these tumors actually have concomitant mutations in FUBP1 and CIC, and nine of these cases are anaplastic oligodendrogliomas." (PMID 23527265, 2013).
colon cancer (2 papers, 2022). "After silencing FUBP1 and overexpressing c-Myc, the malignant biological behaviors and glycolysis was observed in colon cancer cells." (PMID 35546072, 2022). "And declined glycolysis level implied that FUBP1 knockdown also inhibited tumorigenesis and development of colon cancer cells." (PMID 35546072, 2022). "Therefore, this study aimed at identifying the interactions and molecular mechanisms between FUBP1 and c-Myc in colon cancer cells." (PMID 35546072, 2022). "The results indicated that FUBP1 could participate in the deterioration process of colon cancer cells by combining with c-Myc, and it has clinical significance for understanding the key role of FUBP1 in tumor genesis." (PMID 35546072, 2022). "Therefore, the effects and mechanisms of FUBP1 on colon cancer should be studied in animal models in the future." (PMID 35546072, 2022). "In this study, we observed that there was an elevated expression of FUBP1 in colon cancer cells." (PMID 35546072, 2022). "FUBP1 expression was elevated in HCT116 cells relative to other colon cancer cell lines, and silencing FUBP1 could inhibit the ability of HCT116 cells to proliferate, migrate, invade and glycolysis, and enhance its apoptosis." (PMID 35546072, 2022). "The purpose of this work is to analyze FUBP1 expression in colon cancer cells and to explore the impacts of silencing FUBP1 on the ability of colon cancer cells to proliferate, migrate, and invade, as well as apoptosis, glycolysis, and lactic acid production levels, and its internal mechanism." (PMID 35546072, 2022). "Further studies are needed to explore other mechanisms of FUBP1 in colon cancer cells." (PMID 35546072, 2022). "Therefore, the present study aimed to investigate whether FUBP1 could combine with c-Myc to participate in the progression of colon cancer." (PMID 35546072, 2022). "Therefore, this study hypothesized that FUBP1 was involved in the deterioration processes of colon cancer cells through the combination with c-Myc." (PMID 35546072, 2022). "It is also found that FUBP1 expression could be increased in colon cancer tissues, but there is no study on the specific mechanism." (PMID 35546072, 2022).